CXCL12 (C-X-C motif chemokine ligand 12)
Diseases named in the same sentence as CXCL12 in open-access papers (continued):
Sharing a sentence is not in itself a finding about the gene and the disease.
tumor (continued). "CAF secretion of CXCL12/SDF1, M-CSF/CSF-1, IL-6, and CCL2/MCP-1 recruits tumor-associated macrophages (TAM) to the TME and actively differentiates TAMs into an M2 immunosuppressive phenotype." (PMID 31058816, 2019). "Considering its pleiotropic effects in tumour development, the CXCL12/CXCR4 axis is considered as a potential target for cancer treatment." (PMID 31752959, 2019). "By now, there are numerous tumor settings where CXCR4-positive malignant cells are mechanistically likely to metastasize to SDF1 (CXCL12)-expressing organs, such as the bone marrow." (PMID 31418125, 2019). "VCAM1 is one of five genes (CXCL12, MMP2, MMP11, VCAM1, and MME), which were associated with tumor progression, angiogenesis, and metastasis." (PMID 31731625, 2019). "CXCL12 was also shown to recruit endothelial progenitor cells from the bone marrow to the tumor microenvironment where they form a new, functional vessel architecture that re-nourishes the tumor and propagates its regrowth." (PMID 30813533, 2019). "The CXCL12 chemokine attracts hematopoietic cells to the tumor site, stimulating tumor growth, and angiogenesis." (PMID 31417569, 2019). "These interactions showed increased expression of CXCR4 on monocytic MDSCs, with PGE2 inducing CXCL12 in the tumor microenvironment, as well as CXCR4 on MDSC precursor cells." (PMID 31354741, 2019). "Meanwhile, we found that the concentrations of CXCL12 in tumor tissues or tumor tissue culture supernatants (TTCS) were significantly increased when compared to that in non-tumor tissues or non-tumor tissue culture supernatants (NTCS)." (PMID 30808413, 2019). "Next, we evaluated the expression of Vimentin, the predominant intermediate filament of mesenchymal tumor cells, previously found up-regulated in CXCL12-stimulated GBM cells." (PMID 30082913, 2019). "The hijacking of the CXCL12/CXCR4 signaling pathways by tumor cells for the purposes of metastasis and protection from apoptosis rapidly identified the blockade of this axis as a potential treatment target for cancer." (PMID 31428099, 2019). "Since AurA is reported to control tumor cell migration via cytoskeleton reorganization, we evaluated the role of AurA in cytoskeleton protein modification in response to CXCL12 stimulation." (PMID 30082913, 2019). "It has been shown that CAFs as well as tumor cells secrete SDF-1/CXCL12, which is the ligand for CXCR4." (PMID 31663852, 2019). "This upregulation of SHH in the tumor cells in turn lead to higher CXCL12 expression in stromal cells, conferring a bidirectional tumor-stromal feedback loop for tumorigenesis." (PMID 31561620, 2019). "This is based on the capability of the matrix, dermal filler, plus the properties of CXCL12 to develop a suitable pre-metastatic niche with attractive capability for CXCR4 expressing circulating tumor cells." (PMID 31332163, 2019). "It is documented that CXCR4 signaling supports tumor metastasis formation in tissues where CXCL12, its cognate ligand, is abundant." (PMID 30787324, 2019). "Sorafenib treatment induces tumor hypoxia, which upregulates CXCL12 expression in HCA-1 cancer cells and stromal cells." (PMID 31474975, 2019). "When activated by direct contact with leukocytes or secreted factors, including TGF-β, PDGF, FGF2, EGF and CXCL12, CAFs promote tumor growth, increase angiogenesis, degrade ECM to release signaling molecules and promote EMT and metastasis." (PMID 30927930, 2019). "CXCL12/CXCR4 interaction is also known to be involved in tumor-promoting mechanisms which result in increased proliferation, invasion, adhesion, angiogenesis and decreased apoptosis." (PMID 31412792, 2019). "In solid malignancies, CXCL12 was shown to synergize with vascular endothelial growth factor (VEGF) to promote tumor angiogenesis." (PMID 30813533, 2019). "CXC chemokine receptor 7 (CXCR7), a second receptor for CXCL12, has been detected on the surface of multiple types of tumor tissues." (PMID 30636642, 2019).
tumor (continued). "Among inflammatory cytokines, the CXCL12 chemokine plays an important role in tumor-stroma communication." (PMID 31275385, 2019). "The other studies have shown that CXCL12/CXCR4 related axis are involved in tumor metastasis to sites which are characterized by high production of CXCL12, such as lung and bone marrow." (PMID 31500630, 2019). "We found that CXCL12 expression was higher in the metastatic tumor site well compared to the primary site well." (PMID 31628348, 2019). "Numerous studies are trying to shed light upon the tumor roles of CXCL12, such as its effects at cellular levels and interactions with CXCR4 and ACKR3 receptors." (PMID 31275385, 2019). "HIF acts on HREs to promote the expression of CXCR4 on the surface of Tregs cells, which in turn bind to CXCL12 on the surface of tumor cells, and then Tregs are recruited by chemotaxis into tumor tissues." (PMID 30477520, 2018). "In response to hypoxia, stromal cells contained within organized tumors increase secretion of CXCL12, leading to enhanced tumor survival, neovasculogenesis, and recruitment of regulatory populations." (PMID 29485974, 2018). "It is therefore possible that the binding of CXCR4 receptors to CXCL12 during homing to the HSC niche induces integrin expression on the tumor cells, which mediates subsequent adhesion to ECM proteins secreted by the stromal cells at the niche." (PMID 29642534, 2018). "With regard to the second direction of incorporation of CXCR4 antagonist into ICIs therapeutic protocols, several preclinical works have indicated that CXCL12/CXCR4 interactions in the tumor microenvironment mediate immune evasion and resistance to ICIs." (PMID 30257500, 2018). "The group investigated increased CXCL12 expression levels, which correlated with grater tumor size, higher tumor depth, lymphatic invasion, and poor prognosis in GC." (PMID 29867026, 2018). "In cancer, the physiological roles of CXCL12/CXCR4 pathway can be co-opted to promote tumor growth and metastasis." (PMID 29554149, 2018). "The HPCs, along with fibronectin and associated stromal cells, alter the local microenvironment, leading to the activation of other integrins and the secretion of chemokines such as CXCL12 that promote attachment, survival and growth of tumor cells." (PMID 29728125, 2018). "When CXCL12 accumulates within the tumor microenvironment, endothelial cell migration, proliferation, tube formation, and VEGF secretion are all enhanced." (PMID 30591657, 2018). "Tumor microenvironments often contain the chemokine CXCL12 and this was shown to be secreted by CAFs in a murine model of pancreatic ductal adenocarcinoma." (PMID 30420856, 2018). "Neutrophils are recruited at the tumor sites by several chemokine signals, such as CXCL12, CXCL8, CCL3 (MIP-1α), and CXCL6 (huGCP-2), or murine chemokines CXCL1, CXCL2, and CXCL5." (PMID 30591657, 2018). "We focused on signaling by chemokine CXCL12, a hallmark molecule secreted by CAFs, and receptor CXCR4, a driver of tumor progression and metastasis in TNBC." (PMID 29416611, 2018). "MSCs are recruited to and persist in tumors in several models of primary cancers due to the secretion of tumor-derived chemoattractants such as CXCL12, CXCL16, LL37, and cyclophilin B." (PMID 29642534, 2018). "Specifically, we found that targeted ablation of Cxcl12 in Il7-Cre+ stromal cells abrogates the tumor-initiating potential of BC cells and that this niche dependence can be therapeutically harnessed through antagonism of CXCR4." (PMID 29632733, 2018). "High levels of CXCL12 in tumour tissue will invite CXCR4-positive inflammatory, endothelial, and stromal cells into the tumour." (PMID 29887884, 2018). "SDF-1 (CXCL12)/CXCR4 signaling has been described to play a major role in tumor biology, especially in hypoxia adaptation, metastasis and migration." (PMID 30622535, 2018).
tumor (continued). "In this work, it was shown that CXCL9 and CXCL12 are co-expressed in the perivascular area of the tumor, and can form a complex enhancing CXCR4-mediated recruitment of tumor-infiltrating lymphocytes and malignant B cells." (PMID 30319638, 2018). "It has been shown both in tumor models and in our previous work in a cell culture model that the CXCL12/CXCR4 axis promotes the expression of VEGF both at the mRNA and protein levels, most likely through the Akt pathway." (PMID 29751775, 2018). "In cancer, CXCR4 expression and its activation by its endogeneous ligand CXCL12 are key triggers for tumor growth and progression, invasiveness, and metastasis." (PMID 30191351, 2018). "Receptor CXCR4 on cancer cells at the primary tumor site responds to CXCL12/Stromal-derived factor-1α, which is secreted into circulation by osteoblasts, inducing chemotaxis and further homing to and accumulation in the bone." (PMID 29865211, 2018). "Similar to CCL2, CXCL12 recruits immune suppressive myeloid cells to the tumor site-especially MDSC." (PMID 30126117, 2018). "In the present study, we investigated promoter methylation in six genes associated with tumour invasivity (ADAM23, uPA, CXCL12, TWIST1, SNAI1 and SNAI2)." (PMID 30189837, 2018). "Together, these results indicate that miR‐9 knockdown similar to CXCR4 overexpression makes cells responsive to CXCL12 and strongly suggest that miR‐9 tumour‐suppressive effects are mediated via CXCR4 pathway." (PMID 29959873, 2018). "Chemokine CXC motif ligand 12 (CXCL12), which is produced at high levels by cells of the tumour microenvironment and target tissues including lymph nodes, interacts with its signal receptor, CXCR4, expressed on the surface of cancer cells." (PMID 30189837, 2018). "Further, high CXCL12 levels—via the activation of NF-ĸB—suppress the production of TNF-α which subsequently leads to a protection of tumor cells from entering apoptosis." (PMID 30105558, 2018). "Hypoxia significantly impacts on the TAM tumour cell interaction that induces the expression of CXCR4 and its ligand, CXCL12 (SDF-1), further supporting tumour cell dissemination and angiogenesis." (PMID 29507865, 2018). "In a preclinical pancreatic cancer model, it was shown that tumor associated fibroblast-derived CXCL12 mediated ICI resistance by excluding effector T cells from the tumor and that this effect was mitigated by AMD3100 leading to tumor eradication." (PMID 30257500, 2018). "This was proved in in vivo imaging which showed that tumor cells expressing CXCR7 decreased the concentration of CXCL12 in the primary tumor microenvironment." (PMID 29977203, 2018). "There are several studies which attempt to specifically address the role of CXCL12/CXCR4 in mediating tumor osteolysis and tumor growth within bone." (PMID 29930538, 2018). "CXCL12 has multiple roles in tumor pathogenesis by promoting tumor growth, enhancing tumor angiogenesis, suppressing tumor immunity and participating in metastasis of carcinoma." (PMID 29305742, 2018). "CXCL12 is expressed by normal colon epithelial cells; thus, it is possible that this ligand aids the spreading of tumour cells to the normal colon epithelium." (PMID 29887884, 2018). "In particular, the chemokines CCL2, CCL3, IL-8/CXCL8, and CXCL12 are consistently involved in promoting osteoclastogenesis and tumor growth." (PMID 29930538, 2018). "Targeting CAF to reduce production and release of TGFβ, CXCL12, and matrix metalloproteinases (MPP) can limit cancer cell spreading favored by TGFβ and MPP and the anti-apoptotic effect of CXCL12 on tumor cells." (PMID 29515580, 2018). "CXCL12 (C-X-C motif chemokine ligand 12), also known as SDF-1 (stromal cell-derived factor-1), is a critical chemokine involved in tumor metastasis, angiogenesis, cancer cell homing, and proliferation." (PMID 29562664, 2018). "It was shown that CXCL-12 production by tumor cells in mice breast cancer model results in increased macrophage number at the tumor side." (PMID 28660349, 2018).
tumor (continued). "This is associated with the reduced expression of Runt-related transcription factor 2 (RUNX2) and C-X-C motif chemokine 12 (CXCL12) in tumor cells." (PMID 30577536, 2018). "More recently, research has found that high CXCL12 expression in NSCLC tumor cells correlated with high staining of these cells also for phosphorylated CXCR4." (PMID 30257500, 2018). "We verified that the pattern of CXCL12 in all tumor subtypes was the same as the one described for all the cohort, with an increased trend of expression from PT to distant metastases." (PMID 30012106, 2018). "It will be important in future studies to elaborate the processes that determine Cxcl12 induction in a specialized CAF subset during seeding of the tumor niche." (PMID 29632733, 2018). "EGFR over-expression and 19 exon deletion can promote the expression of MMP-2 and MMP-9 by up-regulating CXCR4/CXCL12 signaling pathway, leading to the change of tumor biological characteristics such as higher proliferation, migration and invasion ability." (PMID 30037369, 2018). "The inhibition of CXCL12 by a specific siRNA has reduced tumor infiltration, and the formed tumors had defined borders." (PMID 30123112, 2018). "Our findings demonstrate that Cxcl12 and Myc facilitate glycolysis to promote fast migratory responses during development and repair, and potentially also during tumor invasion and metastasis." (PMID 30202007, 2018). "In the endosteal niche, tumour cells are thought to be held in a quiescent state through CXCR4/CXCL12 interactions using similar mechanisms to those used by osteoblasts to maintain quiescence of HSCs." (PMID 29760166, 2018). "Production of CXCL12, BMPs and Notch by osteoblasts sustains the recruitment of tumour cells in a similar manner to the physiological HSCs recruitment." (PMID 29760166, 2018). "Overall, the level of CXCR4 and CXCL12 expression is predictive for the metastatic potential of a given tumor type and mediates organ-specific metastasis." (PMID 30105558, 2018). "The chemokine CXCL12 (also known as stromal-derived factor-1, SDF-1) plays a critical role of chemoattractant in the tumor niche." (PMID 30380719, 2018). "Many tumor cells have the ability to produce CXCL12, whose extracellular bioavailability can be modulated by the cell-surface expressed CXCR4 and CXCR7." (PMID 29977203, 2018). "Our study showed a similar result which is a tendency of higher CXCL12 levels in tumours at late clinical stages and significant higher CXCL12 levels in the rectum." (PMID 29887884, 2018). "In breast cancer, ACKR3 expressed in trans can modulate CXCL12 levels leading to altered CXCR4-dependent tumor growth." (PMID 29156704, 2017). "It was reported in previous literature that in the tumor microenvironment, CXCL12 secreted by stromal cells or immune cells had an effect on CXCR4 expressed by ECSCs, mediating its invasion and metastasis." (PMID 28193907, 2017). "Excitedly, our results showed QRHX treatment inhibited signaling from tumor cells to macrophages through inducing a remarkable decrease in CXCL12 and CXCR4." (PMID 28630636, 2017). "The increased tumor vascularization observed in MMTV-Wnt1 tumors and revealed by histological analysis was shown to be correlated with higher expression levels of CXCL12, both in tumor myoepithelial and stromal cells." (PMID 29240722, 2017). "Next, we evaluated the effect of HDAC inhibition and CXCL12 re-expression on tumor initiation/maintenance in the APCΔ14/+ mouse model." (PMID 28418886, 2017). "Chemokines such as CCL2, CCL5, CCL7, CCL8, CXCL12 and growth factors, for example, M-CSF, PDGF, and VEGF aggressively recruit blood monocytes at the tumor site, where they distinguish in tumor-associated macrophages." (PMID 29450136, 2017). "The BM stromal niche provides a favorable environment for circulating tumor settlement and growth, in which CXCL12 plays a critical role in tumor cell recruitment and lodgment." (PMID 28423491, 2017).
tumor (continued). "The adhesion molecules ICAM-1, VCAM-1, E-selectin and galectin-3 as well as the chemokine system CXCL12/CXCR4 have been reported to be involved in the interaction of tumor and endothelial cells." (PMID 29100413, 2017). "In the local hypoxic areas of the tumor microenvironment HIF-1α triggers CXCL12 (SDF-1) expression which in turn increases migration, adhesion, and homing of CXCR4+ progenitors." (PMID 28197019, 2017). "In any case, CXCL12 can be found in serum, in tumor capillaries, and in normal tissue at sites of metastasis, including lung and liver as shown in our IHC and." (PMID 29088715, 2017). "To date, it has been well-documented that the interaction between chemokine receptor 4 (CXCR4) and its ligand, stromal cell derived factor-1 (SDF-1, also termed as CXCL12), is closely associated with tumor cells adhesion, invasion and migration." (PMID 28793338, 2017). "CXCL12 induces tumor proliferation, angiogenesis at the tumor site, and invasion, leading in vivo to increased tumor development and metastasis." (PMID 29218300, 2017). "In turn, MSC-like CAFs secreted CXCL12 that binding to CXCR4 on tumor cells induced an EMT, which ultimately promoted metastasis to secondary tumor sites." (PMID 29069870, 2017). "While CXCL12 gradients are typically studied in organized, defined environments, the tumor microenvironment is disorganized." (PMID 29117251, 2017). "Taking together, the data suggested that QRHX inhibited tumor cell-TAMs interactions possibly through blocking CXCL12/CXCR4/JAK2/STAT3 signaling pathways and then regulated macrophages polarization." (PMID 28630636, 2017). "So CXCR4 positive tumour cells move towards the high concentration CXCL12 organs to realize tumour metastasis." (PMID 28403883, 2017). "Our findings show that E5 inhibited the CXCL12-induced migration of vascular endothelial cells in vitro and reduced the formation of tumor vasculature, as evidenced by the downregulated levels of CD31 in vivo." (PMID 29263923, 2017). "Tumor cells expressing CXCR4 that detach from the primary tumor and enter the circulatory system can migrate toward organs that express its ligand CXCL12." (PMID 28191313, 2017). "In conclusion, our work demonstrated that miR-137 serves as a tumor suppressor by inhibition of CXCL12 in human GBM." (PMID 29254162, 2017). "Tumor cells secrete various chemokines such as CXCL12 which recruits regulatory T (Treg) cell and myeloid-derived suppressor cells in tumor microenvironment." (PMID 29207685, 2017). "QRHX treatment blocked the response of macrophages to tumor signals by suppressing CXCL12/CXCR4/JAK2/STAT3 expression and induced a remarkable decrease of the recruitment of M2 macrophages, suggesting the attenuation of M2 subtype cells function by QRHX." (PMID 28630636, 2017). "Organs typical for CXCL12/CXCR4-mediated tumor infiltration, such as bone marrow, brain, lungs and spleens were collected." (PMID 29156704, 2017). "The tumor-promoting effects of CAF are mainly attributed to CXCL12, which is expressed and secreted by CAF, but is also an important SASP component." (PMID 29218300, 2017). "Subsequently, we used bioinformatics analysis and cell transfection to demonstrate the tumor-suppressing effects of miR-137 were due to down-regulation of CXCL12." (PMID 29254162, 2017). "We capture the geometry, cellular environment, and blood dynamics of a small tumor section and examine the magnitude, direction, and time variation of CXCL12 gradients." (PMID 29117251, 2017). "More recently, the CXCL12/CXCR4 axis was reported to be involved in mediating tumour cell invasion and proliferation and to play an important role in tumour angiogenesis, progression, and metastasis." (PMID 28386296, 2017). "The influence of PT on tumor cell adhesion and transmigration onto/through the endothelium as well as its influence on cell adhesion molecules and the chemokine system CXCL12/CXCR4 was investigated." (PMID 29100413, 2017).